IL10 (interleukin 10)
Diseases named in the same sentence as IL10 in open-access papers (continued):
Sharing a sentence is not in itself a finding about the gene and the disease.
infective endocarditis (3 papers, 2018 to 2023). Infective endocarditis (IE) is an infection of the inner lining of the heart chambers (endocardium) and valves. "High serum levels of IL‐17A and IL‐10 often preceded the radiographic diagnosis of infective endocarditis, suggesting potential utility for prioritising diagnostic radiographic imaging." (PMID 32082571, 2020). "High IL‐17A and IL‐10 identified more patients who developed microbiological failure or mortality than were identified by infective endocarditis diagnosis." (PMID 32082571, 2020). "We found that serum IL‐17A, IL‐10 and sE‐selectin are prognostic for persistent bacteraemia and infective endocarditis in patients hospitalised with S. aureus bacteraemia." (PMID 32082571, 2020).
inflammatory skin disease (3 papers, 2016 to 2024). Inflammatory skin disorders covers a broad category that includes many conditions ranging in severity, from mild itching to grave medical health complications These disorders are common in people of all ages and races. "Such iNKT cell-produced IL10 ultimately suppresses inflammatory responses, suggesting palmitate as a promising candidate to treat inflammatory skin diseases." (PMID 36119077, 2022).
intestinal cancer (3 papers, 2013 to 2025). "A previous study has shown that at the completion of chemotherapy treatment for bowel cancer involving Folfox chemotherapy (combination of 5-Fluroruracil, Folic acid and Oxaliplatin), levels of IL-4 and IL-10 were reduced in plasma." (PMID 23951199, 2013).
intracranial aneurysm (3 papers, 2015 to 2024). "Conversely, our result in reverse MR indicated that multiple inflammatory biomarkers, including IL-10, RANTES, MIF, and GRO-alpha, were suggestively affected by intracranial aneurysm and its subtypes." (PMID 38173028, 2024).
iron overload (3 papers, 2015 to 2023). "Increased levels of the remaining pro-inflammatory cytokines or IL-10 have not yet been associated with iron overload or hemochromatosis but could explain the slightly increased NK cell cytotoxicity." (PMID 32327961, 2020).
kidney cancer (3 papers, 2017 to 2025). Primary or metastatic malignant neoplasm involving the kidney. "Interestingly, HHLA2 expression in kidney cancer cells is induced by TME signals in vivo but not in vitro, while monocytes can express HHLA2 in response to certain cytokines, particularly IL-10." (PMID 40255615, 2025).
kidney transplant (3 papers, 2019 to 2025). A surgical procedure in which one or both kidneys from a donor are implanted into a recipient. "Our current study showed that the interaction between gender and IL-10 -1082 affects Tacrolimus DAC in Jordanian kidney transplant recipients during the first month post-transplantation." (PMID 36042898, 2022). "This study aimed to evaluate the levels of FGF23, Klotho, IL-6, IL-10, and Mstn in relation to subjects without comorbidities in stable kidney transplant recipients receiving triple immunosuppressive therapy." (PMID 41303166, 2025). "In terms of the impact of IL2 -330T > G, IL10 -1082G > A, and TNF -308G > A on BPAR incidence, our results are in accordance with previous meta-analyses indicating these SNPs are not significant determinants of BPAR incidence in Caucasian kidney transplant recipients receiving TAC or ciclosporin." (PMID 32153387, 2019).
mental disorder (3 papers, 2022 to 2025). A disease that has its basis in the disruption of mental process. "Our results describe for the first time a quantitative association of IL-10 (-819C/T), TNFA (-308G/A) and ENOS (-786T/C) SNPs of candidate genes markers in cocaine/crack users with mental disorders in a Brazilian sample." (PMID 37274848, 2022). "In conclusion, our results demonstrate the polymorphisms in IL-10 (-819C/T) and TNFA (-308G/A) genes to be associated with the clinical phenotypes of mental disorders in cocaine/crack users." (PMID 37274848, 2022). "In the present study, we hypothesize that IL-10 (-819C/T), TNFA (-30G/A8) and ENOS (-786T/C) polymorphisms can modulate the outcome of mental disorders in cocaine and crack users." (PMID 37274848, 2022).
metastasis (3 papers, 2014 to 2025). The spread or migration of cancer cells from one part of the body (where they first appeared) to another. "The association between the IL-10 −592, −819 and −1082 gene variants and the lymph node metastasis status was also determined." (PMID 24765208, 2014). "Additionally, high levels of IL-10 in peripheral blood have been associated with T3 and T4 stages and lymphatic metastasis, and IL-10 has been linked to poorer prognosis." (PMID 39860614, 2025). "For example, if the role of IL-10 is paradoxical in lung and liver metastasis, IL-10 inhibition can reduce liver metastasis, while adversely, facilitating lung metastasis." (PMID 39681594, 2024).
mucocutaneous leishmaniasis (3 papers, 2019 to 2024). The most common form of leishmaniasis that is transmitted through the bite of female phlebotomine sand flies or after exposure to leishmania parasites. "Thus, a pro-inflammatory response alone is insufficient for the control of infection, since patients with Mucocutaneous Leishmaniasis exhibit an exacerbated inflammatory response with reduced levels of the regulatory cytokine IL-10, yet they are unable achieve cure." (PMID 36704104, 2022).
mucormycosis (3 papers, 2021 to 2025). "Regarding the adaptive immune response, it is known that patients with mucormycosis caused by R. oryzae, and R. pusillus exhibit an immune profile driven by lymphocytes, macrophages, and polymorphonuclear neutrophils (PMNs), triggering responses involving IFN-γ, IL-17A, and IL-10." (PMID 41156648, 2025).
myelodysplastic syndrome (3 papers, 2013 to 2022). A clonal hematopoietic disorder characterized by dysplasia and ineffective hematopoiesis in one or more of the hematopoietic cell lines. "Noteworthy, a previous study evaluated serum levels of TNF-α, IL-6, and IL-10, in diagnostic samples obtained from patients with AML or high-risk myelodysplastic syndromes." (PMID 23616009, 2013).
neuroma (3 papers, 2022 to 2024). A tumor that grows from a nerve or is composed of nerve cells and nerve fibers. "After adding the HUD antibody, the levels of factors secreted by M1 macrophages TNF-α (P < 0.01) and IL-12 (P < 0.05) in co-cultured neuroma cells and monocyte macrophages increased significantly, while the level of factor secreted by M2 macrophage IL-10 (P < 0.05) decreased." (PMID 35294333, 2022). "Furthermore, local inflammation has been heavily implicated in neuroma pain, with upregulation of pro-inflammatory cytokines such as TNF-α and downregulation of IL-10 in painful versus non-painful neuroma tissue samples." (PMID 38749904, 2024).
obstructive sleep apnea (3 papers, 2015 to 2023). "In this context, our study aimed to determine the potential utility of potential biomarkers, such as IL-6, IL-8, IL-10, TNF-α, CRP, and S100B, in the diagnostic process of obstructive sleep apnea (OSA)." (PMID 37762178, 2023). "After the analysis of the levels of pro and anti-inflammatory markers (IL-1β, IL-4, IL-6, IL-8, IL-10, Il-15, TNF-α, CRP, α1-GP) in the tonsils, we observed higher levels of markers IL-8 and IL-10 in pediatric patients with obstructive sleep apnea syndrome." (PMID 30213594, 2020). "Verify the levels of the inflammatory markers, IL-1β, IL-4, IL-6, IL-8, IL-10, IL-15, TNF-α, CRP and α1-GP, in the tonsils of children with and without obstructive sleep apnea syndrome." (PMID 30213594, 2020).
ocular hypertensive (3 papers, 2020 to 2023). "However, it has not been determined whether C3AR1 has an effect on IL10 production or the expression of related genes and proteins in microglia in an ocular hypertensive setting." (PMID 33176797, 2020).
oligoarticular JIA (3 papers, 2010 to 2017). "Similarly, an IL-10 promoter polymorphism that is associated with low IL-10 production (ATA haplotype) has been found to be significantly associated with extended oligoarticular JIA." (PMID 20127724, 2010).
Oral leukoplakia (3 papers, 2014 to 2022). A thickened white patch on the oral mucosa that cannot be rubbed off. "The risk factors (OR) calculated in the present study indicated a 1.82-fold increased susceptibility to LSCC with the presence of AC at IL-10 −592 and −819 (P=0.024), while the OR for vocal leukoplakia was 1.93 (P=0.050)." (PMID 24765208, 2014). "Analogical results were observed in aninvestigation that evaluated levels of IL-10 in patients with oral leukoplakia andhealthy controls (P>0.05)." (PMID 35293553, 2022). "A 1.82-fold increased susceptibility to LSCC was observed with the presence of AC at IL-10 −592 and −819 (P=0.024), while the OR for vocal leukoplakia was 1.93 (P=0.050)." (PMID 24765208, 2014). "Variations in plasma IL-10 concentrations were observed in the patients with LSCC and vocal leukoplakia and in the control group." (PMID 24765208, 2014).
osteonecrosis (3 papers, 2017 to 2019). A none disease characterized by death of bone tissue due to a lack of blood supply. "Previous studies have shown that inflammatory cytokines are increased during the development of steroid-induced osteonecrosis, such as IL-1, IL-2, IL-4, IL-6, IL-10, GM-CSF, IFN-γ, and TNF-α." (PMID 28167850, 2017). "The blood chemistry data in the model group internal system revealed that the expression levels of both anti-and proinflammatory factors (IL-6, IL-10, and TNF-α) significantly increased after osteonecrosis induction, especially at 2 and 6 weeks." (PMID 28931847, 2017). "In the current study, the TLR4/NF-κB pathway and inflammation (IL-6, IL-10, and TNF-α) significantly increased after osteonecrosis induction by LPS with MPS." (PMID 28931847, 2017).
otitis media (3 papers, 2011 to 2016). Inflammation of the anatomical structures of the middle ear, which is most often caused by an infectious process. "Furthermore, there are hints that polymorphism of interleukin-10 (IL-10) also favors the occurrence of otitis media." (PMID 28025605, 2016). "Previous candidate gene studies associated a number of immune system genes with otitis media, which included TNF-α, IL-6, IL-10, Tlr4, surfactant, CD14, FcγRIIa, IFNγ, Eya4, p73, MyD88, Fas, E2f4, Plg, Fbxo11, and Evi1." (PMID 24466073, 2014). "This indicated that the TNF-α, IL-1β, IL-6, IL-8 and IL-10 involved into inflammatory response in otitis media." (PMID 22173336, 2011). "Ginkgo leaf parenteral solution produces its anti-inflammatory effects by inducing the production of IL-10, therefore, administration of Ginkgo leaf parenteral solution could decrease inflammation in rats with otitis media." (PMID 22173336, 2011).
overactive bladder (3 papers, 2022 to 2024). Symptom of overactive detrusor muscle of the urinary bladder that contracts with abnormally high frequency and urgency. "The cytokines with high diagnostic values to distinguish IC/BPS and overactive bladder included IL-10, RANTES, eotaxin, CXCL10, IL-12p70, NGF, IL-6, IL-17A, MCP-1, and IL-1RA." (PMID 35626252, 2022). "Our research revealed significantly reduced IL-10 levels in patients with overactive bladder (OAB) compared to healthy controls, suggesting that these individuals may not have generated an adequate IL-10 response to counteract the inflammation associated with OAB." (PMID 39684342, 2024). "Using different urinary biomarkers including IL-10, RANTES, eotaxin, CXCL10, IL-12p70, NGF, IL-6, IL-17A, MCP-1, and IL-1RA, IC/BPS could be distinguished from overactive bladder." (PMID 36233356, 2022).
peanut allergy (3 papers, 2010 to 2022). "In summary, we demonstrate that constitutive plasma IL-10 levels do not serve as a useful biomarker to discriminate clinical tolerance to peanuts from peanut allergy in humans." (PMID 20567520, 2010).
peripheral arterial disease (3 papers, 2017 to 2025). A disorder of the arteries supplying the upper and lower extremity and the visceral organs. "Lastly, in Caucasian patients with peripheral artery disease receiving elective revascularization, the IL-10ATA haplotypes that are associated with lower serum IL-10 levels correlate with a high risk for postoperative cardiovascular events." (PMID 28659854, 2017). "In both murine and human models of peripheral arterial disease (PAD)—a condition associated with severe ischemic muscle injuries, Tregs potentiated neovascularization through upregulation of IL-10 and amphiregulin expression." (PMID 41459488, 2025). "One study investigated the prognostic relevance of the genetic background of IL-10 in a cohort of patients suffering from peripheral artery disease." (PMID 39199367, 2024). "A small-scale study (n = 48) was conducted with patients with peripheral arterial disease to investigate whether the IL-10 haplotypes (rs1800896, rs1800871, rs1800872) can be utilized as prognostic factors for cardiovascular outcomes." (PMID 39199367, 2024).
placental insufficiency (3 papers, 2012 to 2024). Failure of the placenta to deliver an adequate supply of nutrients and oxygen to the fetus. "This would be in agreement with our observation of significantly different connections between EPO and IL-10 in infants with BW-SDS above or below median, based on the assumption that lower BW-SDS is associated with placental insufficiency and hypoxia." (PMID 39529072, 2024). "IL-12 levels are significantly higher in IUGR with placental insufficiency, while IL-10 levels are significantly lower." (PMID 22110537, 2012). "The lower-level of IL-10 in IUGR with placental insufficiency is interesting as it is perhaps the most important anti-inflammatory cytokine found within the human immune response." (PMID 22110537, 2012). "The IL-12/IL-13 and IL-12/IL-10 ratios are significantly higher in IUGR with placental insufficiency when compared to normal pregnancy (P < 0.04 in both cases)." (PMID 22110537, 2012). "Three of the proinflammatory : anti-inflammatory cytokine ratios are higher in IUGR with placental insufficiency; these are IL-12/IL-10 (P < 0.005), IL-12/IL-4 (P < 0.02), and IL-8/IL-10 (P < 0.01)." (PMID 22110537, 2012). "The IL-12/IL-13 and IL-12/IL-10 ratios are higher in IUGR with placental insufficiency, also suggestive of a stronger inflammatory skew in IUGR with placental insufficiency." (PMID 22110537, 2012). "As IL-10 has profound anti-inflammatory properties, the decreased levels of IL-10 in IUGR with placental insufficiency, may be indicative of a lower proinflammatory bias in this subgroup versus IUGR without placental insufficiency subgroup." (PMID 22110537, 2012). "On the contrary, the anti-inflammatory Th2 cytokine IL-10 is produced at lower levels in IUGR with placental insufficiency (240 pg/mL ± 29) as compared to IUGR without placental insufficiency (421 pg/mL ± 55) (P < 0.01)." (PMID 22110537, 2012). "IL-12 levels were higher and IL-10 levels were lower in IUGR with placental insufficiency than in IUGR without placental insufficiency." (PMID 22110537, 2012). "Three of the ratios are also higher in IUGR without placental insufficiency: IL-12/IL-10, IL-12/IL-4, and IL-8/IL-10." (PMID 22110537, 2012). "However, the IFNγ/IL-10 ratio was actually higher in normal pregnancy than in IUGR without placental insufficiency (P < 0.03)." (PMID 22110537, 2012).
plasmacytoma (3 papers, 1998 to 2016). Plasmacytoma is a localized mass of neoplastic monoclonal plasma cells that represents approximately 5% of all plasma cell neoplasms. "In the meantime, several groups could prevent tumour development—or suppress inflammatory responses in autoimmune patients—by using different sources of exosomes such as plasmacytoma cell-derived exosomes or exosomes derived from IL-10-treated DCs." (PMID 25502465, 2016).
posterior uveitis (3 papers, 2016 to 2022). Inflammation of the choroid as well as the retina and vitreous body. "Topical administration of SOCS1-KIR ameliorated acute and chronic posterior uveitis by inhibiting Th17 cells and the recruitment of inflammatory cells into retina while promoting expansion of IL-10-producing Tregs." (PMID 27703302, 2016).
pseudoexfoliative glaucoma (3 papers, 2020 to 2025). "Earlier, we showed that elevated IOPs were significantly correlated with the intracameral levels of IL-5, IL-6, IL-8, IL-10, IL-15, IL-17, and CCL2 in eyes with pseudoexfoliation glaucoma." (PMID 40353220, 2025).
psychological distress (3 papers, 2022 to 2025). "Reduced neurotrophic support (IGF-1), heightened apoptotic and oxidative signaling (CASP-9 and nNOS), and deficient anti-inflammatory control (IL-10) jointly foster neuronal instability and emotional dysregulation." (PMID 41150816, 2025). "In conclusion, we found that psychological distress was associated with the cytokines IL-2, IL-4, IL-5, IL-10, IL-12, TNF-α, and IFN-γ." (PMID 36405903, 2022). "However, psychological distress was significantly associated with the plasma cytokines IL-2, IL-4, IL-5, IL-10, IL-12, TNF-α and IFN-γ." (PMID 36405903, 2022). "We also found an early increase in levels of anti-inflammatory IL-10 in astrocyte-derived EVs from HCWs with moderate/severe psychological distress." (PMID 40917429, 2025). "Astrocyte-derived EVs from HCWs with moderate/severe psychological distress at the final visit showed high levels of IFN-γ at the 2nd visit (p < 0.01) and IL-10 at each visit (p < 0.01 or p < 0.05) as compared to HCWs with no/low distress." (PMID 40917429, 2025).
pulmonary embolism (3 papers, 2021 to 2024). The obstruction of the pulmonary artery or one of its branches by an embolus, sometimes associated with infarction of the lung. "IL-10 could also play a role in modulating endothelial function: among other cytokines, it significantly increases in adults developing massive pulmonary embolism compared to patients with lower extension of disease." (PMID 34696451, 2021).
pyelonephritis (3 papers, 2013 to 2022). An inflammatory process affecting the kidney. "The regulatory cytokine, Interleukin-10 (IL-10), which is produced during UPEC infection in murine models of UTI and in patients with UPEC cystitis and pyelonephritis, has been a focus of several recent pathogenesis studies." (PMID 24155979, 2013).
retinal diseases (3 papers, 2017 to 2023). "In addition to being potent classifiers, IL-21, IL-10, and ACE may have distinct biological functions in these retinal diseases." (PMID 28128370, 2017).
retinitis (3 papers, 2019 to 2024). Inflammation of the retina. "The same study also suggested a possible role of IL-10 variants on CMV-Retinitis risk among African Americans." (PMID 31396258, 2019).